INS (insulin)
Diseases named in the same sentence as INS in open-access papers (continued):
Sharing a sentence is not in itself a finding about the gene and the disease.
Insulin resistance (continued). "We note that people with high BMI in our cohort had higher insulin production but unchanged glucose disposal during the OGTT, which could signify insulin resistance." (PMID 33740034, 2021). "Interestingly, Fetuin-B levels were associated with estimates of obesity, liver steatosis (HSI), and insulin resistance (high HOMA-IR, low ISIClamp, and weaker insulin-mediated suppression of FFAs (FFASupp))." (PMID 34611132, 2021). "Emerging evidence attributes these alterations mainly to insulin resistance (IR) rather than insufficient secretion of insulin." (PMID 34912824, 2021). "IGFBP3 was shown to trigger insulin resistance independently of IGF binding, supported by decreased GLUT4 translocation to the plasma membrane as well as reduced Akt phosphorylation in response to insulin." (PMID 34690759, 2021). "No metabolic parameters aside from HbA1c were collected, and analysis of possible interactions between changes in performance on the cognitive battery and changes in fasting insulin or insulin resistance is not possible." (PMID 34220427, 2021). "The cut-offs of indices for insulin resistance and insulin sensitivity are controversial, especially in the non-diabetic population." (PMID 33782517, 2021). "Nevertheless, this higher insulin signaling in KO mice do not prevail in the presence of a high caloric intake since feeding a high-fat diet (HFD) for 25 weeks develops similar insulin resistance in both rgs2−/− and wild-type mice." (PMID 33562475, 2021). "The enzyme is regulated by various pathways, not exclusively by insulin, although its insulin induced phosphorylation can be suitable to examine the potential development of insulin resistance." (PMID 33616807, 2021). "Again, these results are not consistent in all conducted studies as other TRE interventions had no notable effect on insulin levels or insulin resistance." (PMID 34456861, 2021). "Insulin resistance as a lack of sensitivity to insulin function in skeletal muscle, liver, and adipose tissue." (PMID 33546744, 2021). "Using a specific JNK inhibitor (SP600125) that could block the kinase activity of JNK, we demonstrated a beneficial effect of JNK inhibition on the insulin signaling pathway and an indispensable role of its activation in FAF1-exacerbated insulin resistance." (PMID 33510836, 2021). "The cell-surface glycoprotein CD44, involved in cell–cell interactions, exhibited higher methylation in VAT of insulin resistance than in healthy individuals, demonstrating that VAT from patients with disturbances in the insulin sensitivity presents a specific DNA methylation pattern." (PMID 33803198, 2021). "The research found that a lack of insulin or insulin resistance leads to accelerated development of sarcopenia." (PMID 34956096, 2021). "We observed the development of peripheral insulin resistance in the absence of α-syn in knockout mice and improvement of insulin sensitivity when α-syn was overexpressed." (PMID 34393754, 2021). "In hepatic insulin resistance, glucose metabolism in hepatocytes does not respond to insulin, but lipogenesis carries on, and triglyceride content increases." (PMID 34445384, 2021). "However, chitosan supplementation decreased plasma tumor necrosis factor (TNF)-α, insulin levels, alanine aminotransferase (ALT) activity, insulin resistance (HOMA-IR), and adipose tissue lipoprotein lipase activity." (PMID 34443619, 2021). "In particular, since the binding of insulin to the insulin receptor (IR) leads to the activation of PI3K/AKT and inactivation of GSK3-β, any disturbance in this transduction pathway will result in insulin resistance." (PMID 34830036, 2021). "In the present study, the peak OGTT glucose level, OGTT AUC and serum insulin concentration were significantly higher in the HFD-induced obese group than the normal group, indicating insulin resistance, impaired glucose tolerance and homeostasis in the latter group." (PMID 34683361, 2021).
Insulin resistance (continued). "Hyperinsulinemia resulting from insulin resistance may increase the bioavailability of insulin-like growth factor (IGF)-1 by lowering IGF-binding proteins, and both insulin and IGF-1 can stimulate the growth of GCa." (PMID 34356646, 2021). "Patients were less insulin-resistant than reported (HOMA-IR: 2.6 ± 1.8; or 2.2 ± 1.3 if those on insulin treatment were excluded) which may be related to co-existing metformin use." (PMID 33794784, 2021). "Recent evidence indicates a negative effect of increased SP on insulin resistance and insulin secretion." (PMID 33917105, 2021). "Insulin resistance (IR) is considered a condition in which the cells of the body do not respond to the action of insulin, so that insulin cannot perform its function." (PMID 35056318, 2021). "IL-6 showed a significant positive correlation with insulin sensitivity and significant negative correlation with insulin resistance and serum glutamate pyruvate transaminase." (PMID 33997590, 2021). "In agreement with the regulatory role of RBP4 in systemic insulin resistance, mice overexpressing RBP4 displayed severe insulin resistance or glucose intolerance 14, 15, while mice with reduced RBP4 levels exhibited increased insulin sensitivity and improved glucose homeostasis." (PMID 34373742, 2021). "Insulin resistance, or BCAA themselves, may also lead to a reduction in insulin clearance, which can further augment availability of circulating insulin." (PMID 33996878, 2021). "T2D, representing close to 90% of overall cases, is characterized by insulin resistance, whereby tissues such as the liver, muscle, and brain do not respond efficiently to insulin resulting in impaired glucose homeostasis." (PMID 34394004, 2021). "Studies reported that the absence of TNF-α improved insulin sensitivity in obese mice, and plasma IL-1 is an important inflammatory marker of systemic insulin resistance." (PMID 34262422, 2021). "It was shown that insulin resistance and inflammation reduce the ability of ASC to differentiate into mature adipocytes by suppressing PPARγ and insulin signaling pathway, leading to adipocyte hypertrophy in order to meet the demand for increased triglyceride storage." (PMID 33536069, 2021). "Collectively, the antioxidant properties and insulin-sensitizing effects of SGLT2 inhibitors could disrupt the interplay between oxidative stress and insulin resistance in T2DM and serve as favorable therapeutic options." (PMID 34439414, 2021). "Of particular interest is that pregnancy decreased insulin sensitivity and increased insulin, insulin resistance, and HbA1c compared with those in nonpregnancy women." (PMID 34603479, 2021). "Indeed, pregnancy-induced insulin resistance adds to the pre-existing insulin resistance, typical of T2DM, and the pre-existing pancreatic β-cell defect compromises the ability to enhance insulin secretion during pregnancy, leading to marked hyperglycaemia." (PMID 33752628, 2021). "The early stage of T2DM is mainly characterized by glucose and lipid metabolism disorder and insulin resistance, and the late stage is mainly characterized by a relative lack of insulin." (PMID 34221088, 2021). "As expected, female mice that consumed the HFD, but not the control diet, developed glucose intolerance, insulin resistance, and alterations in insulin signaling before pregnancy." (PMID 33953835, 2021). "Insulin requirement dose, a common clinical parameter considered to suggest insulin resistance in T1D patients, was not significantly different in patients with and without MS." (PMID 34505411, 2021). "Excessive carbohydrate will induce a large amount of insulin secretion, thereby inducing insulin resistance, which is not conducive to the blood glucose." (PMID 33823815, 2021).
Insulin resistance (continued). "The data showed that PEG-BHD1028 significantly increased glucose uptake in the insulin-resistant C2C12 myotubes in a dose-dependent manner (p ≤ 0.01) relative to untreated or insulin-only treated insulin-resistant cells, implying that PEG-BHD1028 effectively ameliorates insulin resistance." (PMID 33477324, 2021). "Pro-inflammatory cytokines such as IL-1β via oxidative stress induction, reduction of insulin signaling and glucose transport as well as elevation of FFA and up-regulation of hepatic NF-kβ have a central role in acute hepatitis, insulin resistance, glycemia, and dyslipidemia." (PMID 33995940, 2021). "Insulin resistance (IR) is the condition in which the physiological amount of insulin is not sufficient to evoke a proper response of the cell, that is, glucose utilization." (PMID 34684619, 2021). "In addition, circulating adiponectin levels were negatively correlated with the homeostatic model assessment of insulin resistance (HOMA-IR), indicating that increased adiponectin levels positively affect insulin sensitivity in people with obesity." (PMID 33572989, 2021). "The degree of hepatic PPARGC1A methylation was reported to correlate with the measure of insulin resistance, HOMA-IR3, and plasma fasting insulin across NAFLD-affected and healthy individuals, and PPARGC1A was markedly hypermethylated in the livers of NAFLD patients." (PMID 34046015, 2021). "By measuring and simulating the mTORC1 response to insulin in adipocytes derived from healthy humans or type 2 diabetes (T2D) patients, Strålfors and colleagues used ODE-based modeling to investigate mechanisms of insulin resistance." (PMID 33544134, 2021). "The basal glycemia, basal insulin, and mean HOMA index indicated a high prevalence of insulin resistance in the sample: the mean HOMA index was above the threshold of 3, which is considered to diagnose insulin resistance." (PMID 34830503, 2021). "Dyslipidemia is strongly associated to MetS, nonalcoholic fatty liver disease (NAFLD) and is closely related with insulin resistance, since alteration of lipid metabolism and the increase of free fatty acid (FFA) flux inhibits insulin signaling leading to insulin resistance." (PMID 33673200, 2021). "Insulin resistance (IR) is a state when the physiological amount of insulin is not sufficient to evoke proper action, i.e., glucose uptake." (PMID 34207541, 2021). "For example, an FFA2-Gi selective bias agonist might mainly target adipose tissue and improve insulin resistance, whereas an FFA2-Gq/11 bias agonist might improve the release of anorectic hormones in the intestine and increase insulin release in the pancreas." (PMID 32835130, 2021). "Insulin resistance is a systemic disorder in which cells fail to respond to normal levels of circulating insulin." (PMID 33562475, 2021). "In vitro experiments showed that CCN4 could inhibit insulin action in hepatocytes and muscle cells by affecting Akt/FOXO signaling and suggested that CCN4 might induce insulin resistance in the liver and muscle." (PMID 33946738, 2021). "Insulin resistance was recognised in 25 patients (27.47%) on the basis of increased insulin levels in the OGTT, defined as a fasting insulin level above 15 uIU/mL and/or an insulin level at 120 min of above 75 uIU/mL, and in 36 patients (39.56%) with HOMA-IR results >2." (PMID 34300343, 2021). "In fact, it has been reported that fasting insulin resistance may particularly reflect hepatic insulin resistance, whereas OGTT-based insulin sensitivity may be mainly related to peripheral insulin sensitivity." (PMID 34395456, 2021). "However, although our earlier studies showed a clear relationship between insulin resistance and lack of acute gene expression responses to insulin, it is unclear whether obesity itself also is associated with the impaired gene expression response to a single bout of exercise." (PMID 33897458, 2021).
Insulin resistance (continued). "Although, the diagnosis of PCOS does not require insulin level testing, it is clear that abnormal insulin levels and insulin resistance play an important role in the pathogenesis of PCOS." (PMID 34366917, 2021). "The increase in PI3K expression but not INSR expression suggests evidence of insulin resistance and/or an altered insulin signaling pathway in the hypothalamus of this group." (PMID 34248679, 2021). "NRVMs were treated with insulin to induce the cardiomyocyte model of insulin resistance, which is not so representative as cardiomyocytes isolated from the mice model of DCM, because of the difference phenotype of neonatal cardiomyocytes from adult ones." (PMID 33547878, 2021). "Interestingly, the lower HOMA-IR but higher insulin secretion index in the LMF-HSFx group compared to the placebo group, suggesting LMF-HSFx has the potential to attenuate the insulin resistance and to enhance the beta cell repair in NAFLD." (PMID 33809062, 2021). "Fasting insulin is not always an optimal tool for the assessment of insulin resistance in pediatric patients." (PMID 34572220, 2021). "In that study, early TRE improved insulin sensitivity, insulin resistance, β-cell function, and decreased postprandial insulin, however, did not result in a change in FPG." (PMID 33466692, 2021). "Additionally, IGFBP2 was presented as a biomarker of insulin sensitivity and reduced levels of circulating IGFBP2 correlated with insulin resistance." (PMID 34646401, 2021). "Likewise, the homeostasis model assessment of insulin resistance (HOMA-IR) method, which calculates IR by integrating fasting glucose and insulin levels, is less invasive and tedious." (PMID 35056312, 2021). "The reduction in insulin sensitivity has been shown to be mainly related to peripheral rather than hepatic insulin resistance." (PMID 34779405, 2021). "Conversely, the absence of insulin resistance and better insulin secretion is correlated with a better catch-up growth." (PMID 34447729, 2021). "On the other hand, unlike T2DM, genes were more likely to be related to insulin resistance than insulin secretion." (PMID 34834527, 2021). "During hyperglycemia, pancreatic β-cells over-secrete insulin, but it is not able to regulate glucose metabolism due to the presence of insulin resistance; this results in elevated blood glucose levels in T2DM." (PMID 33669133, 2021). "Moreover, anovulation can also be facilitated by insulin resistance, as many anovulatory patients diagnosed with PCOS express ovulatory cycles after treatment with insulin sensitizers such as metformin." (PMID 33679617, 2021). "DM is a metabolic disorder characterized by inappropriate hyperglycemia and can be classified into type 1 DM (T1D), which primarily results from the lack of insulin secretion, and type 2 DM (T2D), which primarily results from insulin resistance (IR)." (PMID 35011666, 2021). "Another interesting aspect that appears to stand out includes no aggravation (absence/repressed) of an inflammation and insulin resistance, in our study, as NF-κB p65 activation induces an inflammatory response and thereby exacerbates insulin sensitivity." (PMID 33930463, 2021). "However, supplementation with melatonin decreased the fastingplasma insulin in OBS+MLT group compared to the untreated obese group.Similarly, insulin resistance was observed in the obese animals compared withcontrol animals." (PMID 34879109, 2021). "As expected, testosterone concentrations were increased in PCOS subjects compared with controls but measures of insulin resistance (insulin AUC and HOMA‐IR) were not different between groups." (PMID 32865246, 2021). "This study aimed to investigate the ethical difference in the relationship between β-cell function and insulin resistance with the homeostasis assessment (HOMA) model calculated from fasting glucose and insulin levels in subjects with NGT in large-scale epidemiological studies." (PMID 34917033, 2021).
Insulin resistance (continued). "Others have shown that a very similar infusion of non-esterified fatty acids and insulin in lean research participants can result in insulin resistance and elevated TNF-alpha, although circulating cytokines were studied only after 48 hours." (PMID 33764994, 2021). "Insulin resistance is observed when peripheral tissues (adipose, skeletal muscle, and liver) do not react correctly to insulin, affecting the uptake of glucose." (PMID 34829598, 2021). "Although the cause and effect relationship between insulin resistance and elevated BCAA is unknown, it is believed that insulin activates BCKD, so insulin resistance leads to the decreased catabolism of the amino-acids." (PMID 34176512, 2021). "Finally, local insulin sensitivity is affected by expressions of SIRT1 and SIRT3, which reduce insulin resistance." (PMID 33806509, 2021). "Insulin resistance in AA compared to CA, at least in lean women, is specific to skeletal muscle; that is, race differences in hepatic insulin sensitivity are not observed." (PMID 34605220, 2021). "First, insulin resistance is brought out by overeating and/or lack of exercise, but enough amount of insulin is secreted so that insulin resistance is compensated." (PMID 33802741, 2021). "In the DIRECT study, a calorie-restricted Mediterranean-style diet reduced plasma insulin and markers of insulin resistance at 24 months, without improvements in fasting glucose and glycated hemoglobin except in participants with type 2 diabetes." (PMID 33919503, 2021). "In persons with prediabetes (impaired fasting glucose, impaired glucose tolerance, without overt hyperglycemia), insulin resistance is compensated by insulin secretion to maintain normoglycemia." (PMID 34943836, 2021). "Insulin dysfunction results from a lack of pancreatic cells to release insulin (Type 1 DM) or an inadequate insulin response (Type 2 DM), both of which are known as insulin resistance (IR)." (PMID 35011387, 2021). "Similarly, genetically predicted insulin secretion was shown to predict CAD (OR 1.83, 95% CI, 1.19–2.62) as well as insulin resistance (OR, 2.35, 95% CI, 1.46–3.53)." (PMID 34677406, 2021). "It is characterized by hyperglycemia, insulin resistance, and relative lack of insulin, frequently accompanied by left ventricular hypertrophy in the patients." (PMID 33510471, 2021). "In line with this notion, LECT2-deficient mice fed an HFD exhibited improved insulin sensitivity in skeletal muscle, as opposed to the mice administered recombinant LECT2 protein, which developed insulin resistance in skeletal muscle." (PMID 34944728, 2021). "Based on the effects of CXCL1/2 immuno-neutralization on insulin signaling, we employed CXCL1 KO mice to evaluate whether this chemokine contributes to HFD-induced insulin resistance." (PMID 34686752, 2021). "That is that improved glucose tolerance, reduced plasma insulin and reduced insulin resistance were not seen in the reported CR responding strain TejJ89." (PMID 34246728, 2021). "The regulatory role of PIK3R2 was reported as ameliorating insulin sensitivity in PIK3R2 knockout mice, while a promoter variant of PIK3CB is reported to provide protection from insulin resistance in obese and non-obese individuals." (PMID 33669862, 2021). "In addition, the serum samples were used to examine fasting insulin (FINS) level and calculated the homeostasis model assessment insulin resistance (HOMA-IR) index." (PMID 34875999, 2021). "We found a physiological deviation of redox balance (oxidative eustress) in obese children without insulin resistance, and a supraphysiological deviation (oxidative distress) in the insulin-resistant group." (PMID 33562490, 2021). "Also, they are involved in the development of insulin resistance and the development of T2DM through their effect on the insulin signaling pathway." (PMID 34344352, 2021).